NLRP3 (NLR family pyrin domain containing 3)
Diseases named in the same sentence as NLRP3 in open-access papers (continued):
Sharing a sentence is not in itself a finding about the gene and the disease.
Sepsis (continued). "The expression of NLRP3 inflammasome mRNA is significantly upregulated in patients with sepsis and various murine models of sepsis and is closely associated with the disease course and the clinical prognosis of sepsis patients." (PMID 34172780, 2021). "Nevertheless, the specific mechanism underlying ERS-induced NLRP3 inflammasome-dependent pyroptosis in sepsis remains to be elucidated." (PMID 34741186, 2021). "As predicted, LPS-induced NLRP3 gene expression was significantly increased in PBMCs with the sepsis-associated risk GG/GC genotypes compared with the CC genotype." (PMID 34172780, 2021). "In accordance with the observation that IL-1β causes myocyte atrophy, Nlrp3-deficient mice are protected against sepsis-induced muscle atrophy." (PMID 34572540, 2021). "EP was also found to inhibit cleavage of IL-1β and NLRP3 inflammasome activation in attenuation of microglial activation in a mice model of sepsis-associated encephalopathy." (PMID 34066647, 2021). "As revealed by these results, the induction of NLRP3 inflammasome through GPR43 inhibition-caused mitochondrial damage by NOX-1 was dominant in determining sepsis-induced inflammatory reactions." (PMID 34584017, 2021). "In summary, this study showed that Arg administration immediately after sepsis increased plasma Arg and NO concentrations, Arg/NO-mediated regulation decreased lipid peroxide levels and downregulated NLRP3 inflammasome-associated protein expressions." (PMID 32454788, 2020). "It has been suggested that bile acids accumulation promoted sepsis-associated inflammation via NLRP3 inflammasome activation." (PMID 32390846, 2020). "Their research also depicted that the FXR-bile acid axis involves in the regulation of cholestasis-associated sepsis, which can be mediated by the negative regulation of NLRP3 inflammasome via the direct binding of FXR to NLRP3 and caspase 1 in macrophages." (PMID 32660430, 2020). "We have previously shown that platelets isolated from a modified CLP rat model of polymicrobial sepsis have increased NLRP3 activation and was associated with renal and pulmonary injury." (PMID 32555710, 2020). "In this section, we confirmed estrogen protects the liver against sepsis-induced damage in mice relating to the suppression of NLRP3 and associated pyroptosis signaling pathway." (PMID 33002070, 2020). "We previously demonstrated that NLRP3 inflammasome activation in sepsis-induced activated platelets was associated with multi-organ injury in the cecal-ligation puncture (CLP) rat model of sepsis." (PMID 32555710, 2020). "GABA type A receptor-associated protein (GABARAP) deficiency led to increased susceptibility to sepsis through the enhancement of mtROS and proinflammatory cytokine expression with NLRP3 inflammasome activation." (PMID 32922385, 2020). "In a CLP-induced sepsis model, NLRP3-deficient mice showed high resolution of inflammation and a high survival rate compared with wild-type mice." (PMID 33182702, 2020). "NLRP3 inflammasome activation was implicated in different systems affected by sepsis, including mitochondrial energetic response, cardiovascular system, gastrointestinal system, renal system, respiratory system, and central nervous system." (PMID 33163006, 2020). "Renal and pulmonary expression of NLRP3 and Caspase 1 were unchanged in response to sepsis, although tissue levels of inflammasome-associated cytokines IL-1β and IL-18 did increase in after CLP." (PMID 32555710, 2020). "What is more, previous studies indicated that NLRP3 inflammasome deficiency or suppression protects against sepsis related injury via suppressing inflammation induced caspase-7 cleavage and pyroptosis or augmenting PKA signaling pathway." (PMID 33002070, 2020). "Taken together, our findings defined a role of T. gondii GRA9 associated with NLRP3 in host macrophages, suggesting its potential as a new candidate therapeutic agent for sepsis." (PMID 33182702, 2020).
Sepsis (continued). "indicate that deficient of NLRP3 augments neutrophils survival by decreasing autophagy and enhancing phagocytosis during polymicrobial sepsis." (PMID 33013364, 2020). "Animal models of sepsis reflects the initial inflammatory response and during this phase a deficiency in NLRP3 augments survival." (PMID 31221993, 2019). "We further show the underlying mechanism of these effects; namely, the sepsis-induced formation of NLRP3 inflammasome leads to caspase-1 activation and triggers inflammatory cascades and pyroptosis." (PMID 30276509, 2019). "In order to investigate the possible causes of NLRP3 impairment during sepsis, we aimed to study the P2X7 receptor in monocytes as this is the receptor for extracellular ATP, the ligand we used to activate the inflammasome in monocytes from septic patients." (PMID 31221993, 2019). "Our study reveals that during the initial inflammatory response in sepsis, septic patients present an early impairment of the NLRP3 inflammasome that is associated with higher mortality." (PMID 31221993, 2019). "We suggest that Nlrp3-mediated IL-1β activation in sepsis is a major pathogenic mechanism in inflammatory muscle atrophy." (PMID 28097512, 2017). "Fatty acid synthase upregulation by bNOS can cause activation of NLRP3 inflammasome during sepsis through the mitochondrial uncoupling protein-2 which is considered as a potential therapeutic target for inflammatory diseases." (PMID 26388860, 2015). "In the present study, severely ill patients with suspected bacteraemia were investigated to find out if genetic variations of the NLRP3 inflammasome influence susceptibility to develop blood stream infection." (PMID 25400921, 2014). "Similarly, puerarin protected against sepsis-associated encephalopathy by inhibiting NLRP3/Caspase-1/GSDMD pyroptosis pathway and reducing blood-brain barrier damage." (PMID 40708650, 2025). "Loss of MMP7 could potentially attenuate sepsis-induced kidney injury through decreased activation of NLRP3 and NLRP6 inflammasomes in the kidney." (PMID 40341670, 2025). "Activation of NLRP3 inflammasomes is associated with various organ (central nervous system, cardiovascular system, respiratory system, gastrointestinal system, and renal system) damages in sepsis." (PMID 40792106, 2025). "These hybrid systems could enhance the inhibition of NLRP3 inflammasome activation and offer more effective therapeutic strategies for sepsis and its associated complications." (PMID 40599085, 2025). "Inhibition of NLRP3 inflammasome-induced pyroptosis could alleviate sepsis-associated intestinal injury." (PMID 40708650, 2025). "Moreover, overexpression of GBP5 in mice exacerbates LPS‐induced sepsis‐associated liver injury through activation of the NLRP3 inflammasome." (PMID 40636987, 2025). "In animal models, IPA is found to effectively ameliorate left heart dysfunction and myocardial inflammation associated with sepsis by modulating the AhR/NF-κB/NLRP3 (aryl hydrocarbon receptor/nuclear factor-kappaB/NOD-like receptor protein 3) signaling pathway." (PMID 40078933, 2025). "It has been reported that NLRP3 inflammasome and its associated signaling pathways may exert regulatory effects on inflammation, autophagy, apoptosis, and pyroptosis in sepsis-induced myocardial dysfunction." (PMID 39887250, 2025). "Indeed, we and others have reported that CLP-sepsis causes both the activation of NLRP3 inflammasome and proteolytic cleavage of pro-caspase-1 to its active form caspase-1, finally leading to IL-1β maturation and release." (PMID 39559354, 2024). "Additionally, exploring the potential of gene silencing of NLRP3 reveals promising outcomes, as it appears to diminish neutrophilic infiltrate and associated liver damage induced by sepsis." (PMID 38294676, 2024). "Because FXR reportedly interacted with NLRP3 in cholestasis-associated sepsis, we investigated whether FXR has the same function in NEC." (PMID 39013030, 2024).
Sepsis (continued). "Furthermore, NLRP3 has been shown to be helpful in predicting the risk of sepsis at an early stage, particularly in patients with septic shock." (PMID 38716051, 2024). "Moreover, BAs, proven to be DAMPs, can activate NLRP3 inflammasome during cholestasis-associated sepsis and FXR plays pivotal roles in sepsis and endoplasmic reticulum (ER) stress by controlling the NLRP3 inflammasome." (PMID 38172440, 2024). "ROC analysis showed the diagnostic values of serum NLRP3 concentration for ARDS in sepsis patients." (PMID 37649483, 2023). "NLRP3 knock-out mice were protected from several aspects of sepsis and age-related dysfunction, while NLRP3 over-expression contributed to “sterile” inflammation and wasting in models of aging, Duchenne-associated muscle atrophy and sepsis." (PMID 37447158, 2023). "More and more studies have shown that NLRP3-meditated pyroptosis may cause vital injury in different organs affected by sepsis." (PMID 36998049, 2023). "Moreover, inhibition of NLRP3 inflammasome mediates the cytoprotective effects in sepsis-associated myocardial injury." (PMID 37596540, 2023). "Consequently, microglial and NLRP3 activation is associated with the severity of sepsis-associated encephalopathy." (PMID 36769140, 2023). "Activation of the inflammasome, particularly the nucleotide-binding oligomerization domain and leucine-rich repeat pyrin domain-containing protein (NLRP)-3, is central to the process of uncontrolled inflammation and the pathogenesis of sepsis and sepsis-associated ALI or ARDS." (PMID 38027963, 2023). "NLRP3 inflammasome is regarded as a target of septic cardiomyopathy and its inhibition mediated the cytoprotective effects and improved myocardial function in sepsis-associated myocardial injury." (PMID 37596540, 2023). "In macrophages, the NLRP3 inflammasome plays a crucial role in the defense against pathogenic invasions Abnormal activation of the NLRP3 inflammasome promotes cardiovascular dysfunction, type 2 diabetes, septicemia, novel coronavirus infection, and other inflammatory diseases." (PMID 38193078, 2023). "The effects of PD on Sirt3/NLRP3 pathway associated protein in sepsis mice." (PMID 37494665, 2023). "Our results showed that cyasterone suppressed NLRP3 inflammasomes activation, suggesting that cyasterone protects against sepsis-associated ALI and may be related to inhibiting NLRP3 inflammasomes activation." (PMID 37853474, 2023). "In conclusion, our data suggest that serum NLRP3 might be a useful diagnostic and prognostic biomarker for sepsis patients complicated with ARDS." (PMID 37649483, 2023). "In addition to PAMPS and DAMPS that bind to TLRs on the cell surface, the cytoplasmic NOD-like receptor protein 3 (NLRP3) inflammasome is integrated to the inflammatory cascade in sepsis-associated AKI." (PMID 36674930, 2023). "However, future studies should be done to investigate the mechanisms underlying the association between serum NLRP3 levels and sepsis complicated with ARDS." (PMID 37649483, 2023). "Therefore, the present study aimed to study the diagnostic value of serum NLRP3 concentration for ARDS in sepsis patients, and the predictive value of serum NLRP3 concentration at the time of diagnosis for death 28 days after treatment." (PMID 37649483, 2023). "Moreover, high serum NLRP3 levels at admission are associated with increased mortality, severity of sepsis, and risk factors for ARDS, which has important reference significance for clinical diagnosis and prognosis evaluation." (PMID 37649483, 2023). "Our study demonstrated that the serum NLRP3 concentration might be a useful diagnostic and prognostic biomarker for sepsis patients complicated with ARDS." (PMID 37649483, 2023). "Moreover, analysis of NLRP3 29940G>C SNPs in clinical sepsis populations revealed that this gain-of-function mutation suppressed NLRP3 expression and downstream inflammatory cytokine responses, which protected patients against poor clinical outcomes." (PMID 36636720, 2022).
Sepsis (continued). "In addition to transcriptional regulation, FXR was found to directly interact with NLRP3 and caspase 1, negatively regulating the NLRP3 inflammasome in cholestasis-associated sepsis." (PMID 36405253, 2022). "For instance, the inhibition of the NF-kB/NLRP3 inflammasome signaling pathway by Maf1 could lead to attenuation of sepsis-associated encephalopathy." (PMID 35508474, 2022). "A panel of combined markers further yielded 100% sensitivity and specificity, suggesting that the combination of IL-31, IL-1β, and NLRP3 may provide a promising diagnostic and prognostic panel for sepsis." (PMID 35967871, 2022). "Previously noted, TXNIP exhibit a protective negative regulatory role on NO production, induction of iNOS expression as well as on NF-κB activation, while in TXNIP-deficient mice, increased sepsis susceptibility proceed despite reduced IL-1β processing by S-nitrosylation of NLRP3." (PMID 34824200, 2021). "More and more studies have shown that NLRP3-meditated pyroptosis may cause vital injury in different organs affected by sepsis including liver injury." (PMID 33860064, 2021). "Therefore, p47phox activated ROS-induced mitochondrial damage to cause GPR43 inhibition to induce NLRP3 Inflammasome activity in sepsis-induced inflammatory reactions model." (PMID 34584017, 2021). "Since autophagy and inflammation are tightly connected, the reduced autophagy flux could lead to an increased inflammatory response to NLRP3 inflammasome activation and LPS-induced sepsis in CstC-deficient BMDMs and mice." (PMID 34440840, 2021). "Therefore, it is of great importance to explore the specific intracellular pathways associated with NLRP3 inflammasome-related pyroptosis during sepsis." (PMID 34741186, 2021). "The NLRP3 inflammasome serves as a major component of innate immunity and is regarded as a potential therapeutic target for treating inflammation-associated diseases, including sepsis." (PMID 34207356, 2021). "In accordance with the expected results, we observed a significant increase in the expression levels of pyroptosis-related markers in the liver of CD38-deficient septicemia mice, such as NLRP3, cleaved caspase-1, IL-1β, and IL-18, accompanied by the increase in cleaved caspase-3." (PMID 33860064, 2021). "NLRP3 activity status has been examined in in vivo murine renal inflammation models, LPS-evoked acute lung injury, adipose tissue inflammation, and sepsis-associated encephalopathy, amongst many others." (PMID 34443594, 2021). "D+L group could significantly increase the level of Cav-1 protein and decrease the level of TLR-4 and NLRP3 protein in liver tissue caused by sepsis." (PMID 33558888, 2021). "Furthermore, PBMCs with the sepsis-associated risk allele 29940G in NLRP3 exhibited significantly enhanced expression of NLRP3 and release of IL-1β and TNF-α compared to those with the C allele under LPS stimulation." (PMID 34172780, 2021). "This study uncovers a novel role of the NLRP3-IL-1β signaling pathway in gauging the severity of sepsis-associated inflammation and determining whether acute neuroinflammation will resolve or transition to low grade chronic neuroinflammation." (PMID 32070376, 2020). "Thus, this study will provide the first evidence unveiling a novel role NLRP3-IL-1β axis in mediating sepsis-associated brain immune dynamic changes." (PMID 32070376, 2020). "Deficient autophagy was associated with increased NLRP3 inflammasome assembly and culminated caspase-1 activation as observed in sepsis, enabling enhanced cleavage of pro-IL-1β and pro-IL-18 into their biologically active forms IL-1β and IL-18 in DSS-treated UVRAGFS mice colons." (PMID 31831743, 2019). "The revelation of NLRP3 activation in platelets in sepsis may uncover additional mechanisms that could contribute to improved outcomes in sepsis associated with NLRP3 inhibition." (PMID 31054188, 2019).
Sepsis (continued). "We hypothesized that the NLRP3 inflammasome is activated in platelets during sepsis and may be associated with multiorgan injury in response to polymicrobial sepsis." (PMID 31054188, 2019). "In this study, we hypothesized that the genetic variations in the NLRP3 gene might affect the magnitude of immune inflammatory responses following trauma, which subsequently determines the susceptibility to sepsis and MODS in patients with major trauma." (PMID 22112657, 2011). "In addition, the expression of the NLRP3 inflammasome mRNAs has been shown to be well associated with the outcomes of patients with sepsis." (PMID 22112657, 2011). "Abnormal activation of the inflammatory body NLRP3 is associated with many inflammatory diseases, and sepsis-triggered typical inflammasome depends on the NLRP3/caspase-1 pathway to mature and secrete IL-1β, which may lead to the reduced generation of new neurons." (PMID 40218223, 2025). "In addition, Nlrp3 deficiency strikingly attenuated sepsis-associated acute kidney injury." (PMID 37759588, 2023). "In this study, the protein levels of NLRP3, Caspase 1 p20, and IL‐1β in the myocardium of mice from the NR1H3‐KO + CLP group were significantly higher than those from the WT + CLP group, suggesting that NR1H3 deficiency could lead to activation of NLRP3 signaling pathways during sepsis." (PMID 37206244, 2023). "Importantly, circulating IL-18 and mitochondrial DNA, a DAMP associated with NLRP3 inflammasome activation, were significantly elevated in plasma from human patients critically ill with diseases such as sepsis and sepsis-induced ARDS, and significantly associated with ICU mortality." (PMID 36232959, 2022). "NLRP3 is a cytosolic immune signaling receptor which leads to caspase-1 mediated cleavage and activation of IL-1B and IL-18 and has been implicated in the pathogenesis of inflammatory disease processes like asthma, Parkinson’s, inflammatory bowel disease and sepsis." (PMID 34638670, 2021). "However, little is known about the clinical relationship of the NLRP3 genetic variations with sepsis susceptibility and development, and the underlying mechanisms involved in the regulatory effects of these genetic variants on sepsis-induced inflammatory processes remain to be explored." (PMID 34172780, 2021). "IL-1β released by the mtROS/NLRP3 inflammasome pathway in platelets has been correlated with increased vascular permeability, which may cause irreversible shock during sepsis." (PMID 33324236, 2020). "Thus, NLRP3 may mediate persistent platelet activation to cause the overactive immune response characteristic of sepsis." (PMID 32555710, 2020). "Thus platelets may potentially contribute to the development of renal and pulmonary injury in sepsis through modulation of the immune response through NLRP3 associated cytokines." (PMID 31054188, 2019). "Since not only sepsis is associated with inflammation-induced muscle failure and increased IL-1β levels other forms of muscle atrophy might also profit from Nlrp3/IL-1β inhibition; for example, in patients with rheumatoid arthritis and inflammatory bowel disease." (PMID 28097512, 2017). "In acute lung injury caused by sepsis, phosphorylated STAT3 recruits EP300 to form a complex that promotes the acetylation of histones H3 and H4 at the NLRP3 promoter, leading to cellular pyroptosis." (PMID 41513612, 2026). "In summary, SNX10 downregulation mitigated sepsis-induced oxidative stress and pulmonary inflammation by inhibiting the NF-κB/NLRP3 pathway." (PMID 41711764, 2026). "A study of sepsis-induced muscle atrophy in a mouse model revealed that the NLRP3 inflammasome participates in regulating muscle atrophy, as NLRP3-KO mice exhibited less severe muscle atrophy and lower serum IL-1β levels than WT mice." (PMID 41399377, 2026). "In the CLP mouse model, inhibiting the NLRP3/IL-1β pathway alleviates sepsis-induced cardiac muscle atrophy and cardiomyopathy." (PMID 41334559, 2025).